TMEM165 (transmembrane protein 165)
Description:
Putative divalent cation:proton antiporter that exchanges calcium or manganese ions for protons across the Golgi membrane. Mediates the reversible transport of calcium or manganese to the Golgi lumen driven by the proton gradient and possibly the membrane potential generated by V-ATPase. Provides calcium or manganese cofactors to resident Golgi enzymes and contributes to the maintenance of an acidic luminal Golgi pH required for proper functioning of the secretory pathway (By similarity). Promotes Ca(2+) storage within the Golgi lumen of the mammary epithelial cells to be then secreted into milk (By similarity). The transport mechanism and stoichiometry remains to be elucidated.
Synonyms: TPARL; TMPT27; GDT1; SLC64A1; CDG2K; FT27
Tractability: Antibody: UniProt predicts a signal peptide or a membrane-spanning region. PROTAC: ubiquitination databases record sites on it; its protein half-life has been measured.
Safety:
Unwanted effects reported when the protein is acted on. In parentheses: how it was acted on, where the effect was seen, and who reports it.
sleep disturbances (source: ClinPGx)
Gene: Protein-coding gene on chromosome 4 (55,395,652 to 55,453,397, forward strand). Ensembl gene ENSG00000134851.
Subcellular location: Golgi apparatus membrane
Subcellular location (Human Protein Atlas): Golgi apparatus
Gene Ontology:
Molecular function: metal ion transmembrane transporter activity
Biological process: calcium ion transport; Golgi calcium ion transport; manganese ion transport; Golgi calcium ion homeostasis
Cellular component: endosome membrane; Golgi apparatus; lysosomal membrane; trans-Golgi network membrane; cis-Golgi network membrane; Golgi membrane
Genetic constraint (gnomAD): Loss-of-function variants: 16 observed, 22.68 expected, observed/expected ratio (o/e) 0.71, 90% interval 0.48 to 1.07. The upper end of that interval is the gene's LOEUF score, 1.07, which puts it in group 4 of 6, group 1 being the genes least tolerant of losing a copy. Missense variants: 303 observed, 337.96 expected, observed/expected ratio (o/e) 0.9, 90% interval 0.81 to 0.99. Synonymous variants: 151 observed, 127.05 expected, observed/expected ratio (o/e) 1.19, 90% interval 1.04 to 1.36.
Gene-disease validity (ClinGen):
ClinGen rates the evidence that TMEM165 causes each of these diseases.
TMEM165-congenital disorder of glycosylation (autosomal recessive): Moderate.
Homologues: Orthologues: chimpanzee TMEM165 (100% identical), pig TMEM165 (94% identical), dog TMEM165 (93% identical), rat Tmem165 (92% identical), mouse Tmem165 (92% identical), guinea pig TMEM165 (91% identical), rabbit TMEM165 (88% identical), macaque TMEM165 (82% identical), zebrafish tmem165 (69% identical), tropical clawed frog tmem165 (68% identical), Caenorhabditis elegans Y54F10AL.1 (47% identical), Drosophila melanogaster CG42542 (46% identical).
Diseases named in the same sentence as TMEM165 in open-access papers:
TMEM165 is named in the same sentence as 30 diseases in open-access papers, as found by Europe PMC text mining. Sharing a sentence is not in itself a finding about the gene and the disease. The quoted sentences say what the papers report.
congenital disorder of glycosylation (9 papers, 2014 to 2024). Congenital disorder of glycosylation (CDG) is a fast growing group of inborn errors of metabolism characterized by defective activity of enzymes that participate in glycosylation (modification of proteins and other macromolecules by adding and processing of oligosaccharide side chains). "For instance, mutations in the gene encoding Transmembrane protein 165 (TMEM165) were discovered as a cause of a new type of congenital disorder of glycosylation (CDG)." (PMID 39002685, 2024). "Recent studies have demonstrated that mutation in TMEM165 gene is associated with the rare autosomal recessive disorder “congenital disorders of glycosylation “(CDG) development in the affected people." (PMID 34703799, 2021). "The interest for this protein family arose in 2012 when its human member TMEM165 was linked to the occurrence of Congenital Disorders of Glycosylation (CDGs) when harbouring specific mutations." (PMID 32743000, 2020). "A defect in the TMEM165 gene is known to cause a subtype of Congenital Disorder of Glycosylation (CDG), a group of rare diseases associated with impaired protein glycosylation." (PMID 27075443, 2016). "Indeed, mutations of TMEM165 found in patients with congenital disorder of glycosylation (CDG) type II hamper the transport function or localization of TMEM165." (PMID 35901096, 2022). "TMEM165 deficiency has been shown to cause a new type of Congenital Disorder of Glycosylation (CDG), a family of inborn metabolic diseases affecting the glycosylation pathway." (PMID 24955841, 2014). "Congenital disorder of glycosylation (CDG), type IIk or TMEM165-CDG, is caused by biallelic mutations in TMEM165." (PMID 34220933, 2021). "In this line, we first describe the Transmembrane protein 165-Congenital Disorder of Glycosylation (TMEM165-CDG) and Friedreich ataxia pathologies." (PMID 31319631, 2019). "A second, the human transmembrane protein 165 (TMEM165), attracted much interest when its involvement in the rare condition known as congenital disorders of glycosylation (CDG) was demonstrated in 2012." (PMID 34194462, 2021).
hepatocellular carcinoma (3 papers, 2020 to 2024). A malignant tumor that arises from hepatocytes. "Similarly, in hepatocellular carcinoma, TMEM165 is overexpressed in cancer cells, promoting invasive activity." (PMID 39002685, 2024). "Indeed, TMEM165 was found overexpressed in hepatocellular carcinoma and involved in cancer invasive activity, through a mechanism that still needs to be uncovered." (PMID 32743000, 2020). "A previous study observed increased expression of TMEM165 in hepatocellular carcinoma (HCC) and knockdown of TMEM165 in HCC led to a decrease in invasive disease." (PMID 32733646, 2020).
breast carcinoma (2 papers, 2020 to 2024). "Thus, we postulate that TMEM165 plays a key role in modulating breast cancer invasion by altering N-linked glycosylation leading to the suppression of E-cadherin levels." (PMID 32733646, 2020). "Therefore, we want to evaluate whether TMEM165 alters N-linked glycosylation in breast cancer cells." (PMID 32733646, 2020). "For example, breast cancer cells show higher TMEM165 levels compared to normal cells, and increased TMEM165 expression correlates with worse outcomes in breast cancer patients." (PMID 39002685, 2024). "Our TCGA expression analysis indicates that certain ER+ breast cancers do express increased TMEM165 although the overall percentages of luminal A and luminal B cases with TMEM165 expression are lower than breast cancers that are negative for ER receptor." (PMID 32733646, 2020). "The current study has extended our previous discovery and demonstrates that TMEM165 induces glycosylation changes and protein expression changes in breast cancer that favors EMT." (PMID 32733646, 2020). "Previously, we identified TMEM165 as a potential biomarker for breast carcinoma in a glycoproteomic study using late stage invasive ductal carcinoma tissues with patient- matched adjacent normal tissues." (PMID 32733646, 2020). "We are the first to report that increased expression levels of TMEM165 in IDC tumors correlates with poor prognosis in breast cancer patients." (PMID 32733646, 2020). "In conclusion, we have expanded on our initial 2012 glycoproteomic study that was the first to identify TMEM165 protein as a potential biomarker for breast carcinoma." (PMID 32733646, 2020). "The substantial number of cases with increased TMEM165 expression led us to evaluate the prognostic significance of TMEM165 expression in breast cancer using the TCGA data." (PMID 32733646, 2020). "We have examined the levels of TMEM165 in ER- and ER+ metastatic TCGA breast cancer cases and find that there are significantly higher TMEM165 levels in ER- metastatic cases (p 0.009)." (PMID 32733646, 2020). "Cumulatively, these results indicate that TMEM165 promotes the growth and invasion of breast cancer." (PMID 32733646, 2020). "We observed an inverse correlation between the protein expression levels of TMEM165 and E cadherin in several human breast cancer cell lines." (PMID 32733646, 2020). "The expression profile of TMEM165 among the histological subtypes of invasive breast cancer indicate that TMEM165 expression occurs in all subtypes with the highest percentages in the ER negative subtypes (IDC subtypes)." (PMID 32733646, 2020). "In the present study, we report that TMEM165 is upregulated in human breast cancer cell lines and patient tumor tissues and increased expression of TMEM165 correlates with poor prognosis in breast cancer patients." (PMID 32733646, 2020). "In this study we have provided initial mechanistic studies that indicate that TMEM165 expression drives the growth and invasion of breast cancer." (PMID 32733646, 2020). "Collectively, our data demonstrate that overexpression of TMEM165 promotes EMT in breast cancer suggesting a novel role for TMEM165 as a driver of tumor invasion making it a prognostic marker and potential therapeutic target for breast cancer." (PMID 32733646, 2020). "This study is also the first to use CRISPR/Cas9 gene editing to delete TMEM165 in a human breast cancer cell line." (PMID 32733646, 2020). "We find that TMEM165 is amplified across all types of breast cancer compared to normal breast tissue with IDC cases having the highest levels of TMEM165 expression." (PMID 32733646, 2020). "Using a CRISPR/Cas9 mediated TMEM165 knockout in the human breast cancer cell line MDAMB231 we find that TMEM165 deletion impaired invasive and migratory properties in vitro and tumor growth in vivo." (PMID 32733646, 2020). "We have analyzed TCGA breast cancer cases to examine TMEM165 expression levels in all molecular types of human breast cancer using UALCAN." (PMID 32733646, 2020).
breast carcinoma (continued). "We find that IDC patients with higher TMEM165 expression levels have reduced overall survival making this protein a target for the development of new therapeutic strategies to limit the progression of breast cancer." (PMID 32733646, 2020). "We have analyzed TMEM165 expression across a panel of human breast cancer cell lines." (PMID 32733646, 2020). "Next we looked at expression levels for TMEM165 in the TCGA breast carcinoma database." (PMID 32733646, 2020). "Our analysis of TMEM165 expression levels in human breast cancer cell lines suggests that there may be a relationship between ER expression and the control of TMEM165 expression levels." (PMID 32733646, 2020). "Our hypothesis is that the TMEM165 protein confers a growth advantage to breast cancer." (PMID 32733646, 2020). "In breast cancer, we find that TMEM165 is amplified in expression with no identified mutations." (PMID 32733646, 2020). "Human breast cancer cell lines with ER expression have undetectable levels of TMEM165 by RT-PCR and Western blot; while cell lines without ER expression have higher levels of TMEM165." (PMID 32733646, 2020).
invasive breast carcinoma (2 papers, 2020 to 2022). A carcinoma that infiltrates the breast parenchyma. "Knocking out the TMEM165 gene in human invasive breast cancer cell line MDAMB231 attenuated malignant properties of the cells, whereas its overexpression triggered a more mesenchymal phenotype." (PMID 35892570, 2022). "We created a CRISPR/Cas9 knockout of TMEM165 in the human invasive breast cancer cell line MDAMB231." (PMID 32733646, 2020). "Our discovery of increased expression of TMEM165 in invasive breast cancer led us to investigate the potential role of TMEM165 in cell migration." (PMID 32733646, 2020). "The TMEM165 protein was identified by mass spectrometry in invasive breast carcinoma tissue with no detection in patient-matched adjacent normal breast tissues." (PMID 32733646, 2020).
Danon disease (1 paper, 2025). A lysosomal glycogen storage disease characterized by severe cardiomyopathy and variable degrees of muscle weakness, frequently associated with intellectual deficit. "Danon disease is caused by loss of LAMP2 itself, rather than a glycosylation defect, but the observed LAMP2 underglycosylation in TMEM165-depleted cells suggests an avenue by which TMEM165 dysfunction might indirectly affect lysosomal proteins relevant to cardiac pathology." (PMID 41583011, 2025).
diaphyseal dysplasia (1 paper, 2017). "TMEM165-CDG, a type II CDG, combines impaired N and O-glycosylation and manifests with striking osseous changes as epiphyseal, metaphyseal, and diaphyseal dysplasia." (PMID 29112118, 2017).
ductal carcinoma in situ (1 paper, 2020). "In this preliminary study we have investigated the expression of TMEM165 in earlier stage invasive ductal carcinoma and ductal carcinoma in situ cases." (PMID 32733646, 2020).
dwarfism (1 paper, 2021). "The major clinical findings in the individuals with a homozygous splice mutation leading to total loss of TMEM165 protein are severe psychomotor retardation, major skeletal dysplasia, and pronounced dwarfism." (PMID 34930890, 2021). "Altogether, these data bring evidence that TMEM165 deficiency promotes premature chondrocyte maturation and hypertrophy, a process which affects endochondral ossification and may lead to dwarfism." (PMID 34930890, 2021).
dysplasia (1 paper, 2021). A usually neoplastic transformation of the cell, associated with altered architectural tissue patterns. "TMEM165 deficiency leads to skeletal disorder characterized by major skeletal dysplasia and pronounced dwarfism." (PMID 34930890, 2021).
invasive ductal breast carcinoma (1 paper, 2020). The most common type of invasive breast carcinoma, accounting for approximately 70% of breast carcinomas. "TMEM165, a Golgi membrane protein, was discovered as a potential biomarker for invasive ductal breast carcinoma in our previous glycoproteomic study." (PMID 32733646, 2020).
myocardial infarction (1 paper, 2023). Gross necrosis of the myocardium, as a result of interruption of the blood supply to the area, as in coronary thrombosis. "Regarding myocardial infarction, a study of high-throughput RNA sequencing found that 3,862 circRNAs are dysregulated in peripheral blood, and the differentially expressed circ-TMEM165, circ-UBAC2, circ-ZNF609, circ-ANKRD12, and circ-SLC8A1 are confirmed in the AC16 cell model." (PMID 37840751, 2023).
neuroblastoma (1 paper, 2025). Neuroblastoma (NB) is the most common solid, extracranial childhood tumor. "These genes included neuroblastoma-amplified sequence (NBAS), ETS variant transcription factor 6 (ETV6), transmembrane protein 165 (TMEM165), collagen type IV alpha-3-binding protein (C43BP), serine/threonine-protein phosphatase 5 (PPP5), and short-chain specific acyl-CoA dehydrogenase (ACADS)." (PMID 39400548, 2025).
psychomotor delay (1 paper, 2025). "Reported TMEM165-CDG cases frequently include global developmental/psychomotor delay (e.g., psychomotor delay/hypotonia, seizures) and CNS abnormalities (e.g., white-matter changes)." (PMID 41583011, 2025).
cancer (6 papers, 2017 to 2024). A tumor composed of atypical neoplastic, often pleomorphic cells that invade other tissues. "In murine models, TMEM165 overexpression was associated with increased invasive activity in certain types of cancer." (PMID 39002685, 2024). "Among the upregulated genes, ADAM10 (encodes a zinc-dependent protease) and TMEM165 (encodes a Golgi body transmembrane protein) have been reported to promote the invasion of tumor cells in multiple cancer types." (PMID 35816095, 2022). "In addition to CDGs, TMEM165 has been linked to other human diseases, particularly cancer." (PMID 39002685, 2024). "However, recent findings on the involvement of TMEM165 in cancers and the association of specific polymorphisms with mental health disorders strongly suggest that alterations in TMEM165 expression could play significant, tissue-specific, roles in various pathologies." (PMID 39002685, 2024). "CEP85L-ROS1 and TMEM165-PDGFRA were reported by a previous study that defines the landscape of kinase fusions in cancer." (PMID 32466770, 2020). "Overexpression of TMEM165 has been observed in various types of cancers." (PMID 39002685, 2024). "Besides causing CDG, recent investigations have demonstrated the functional involvement of TMEM165 in several other pathologies including cancer and mental health disorders." (PMID 39002685, 2024). "We were also able to glean some valuable information from a prominent TIC (TMEM165-CLOCK), which may provide insights into the transformation of primary cancers to metastatic cells." (PMID 30674975, 2019). "TMEM165 is suggested to be involved in congenital disorders of glycosylation (CDG), but, so far, no connection with cancer risk has been investigated." (PMID 28177907, 2017).
tumor (5 papers, 2012 to 2025). "Our results indicate that removal of TMEM165 in these cells results in a significant reduction of cell migration, tumor growth, and tumor vascularization in vivo." (PMID 32733646, 2020). "Subsequently, we performed quantitative reverse-transcription polymerase chain reaction (qRT-PCR) to examine the expression levels of the seven key prognostic genes—CEBPB, TANK, MAT2B, TMEM165, CCDC167, CYFIP1, and COX17—in the CEBPB+CAF prognostic model in the tumor tissues." (PMID 40145099, 2025). "Of note,TMEM165 has been found to be up-regulated in invasive GBM cells with transcriptional differences between these and the other core tumor cells, supporting a role for this gene in tumor invasion." (PMID 23029397, 2012).
infection (2 papers, 2021 to 2025). The state of being infected such as from the introduction of a foreign agent such as serum, vaccine, antigenic substance or organism. "In concordance with the viability screen, TMEM165 was the most enriched gene for the early infection screen." (PMID 40815167, 2025). "For both screens, the most highly enriched host factor that provided protection from infection was transmembrane protein 165 (TMEM165), a protein known to be involved in trafficking to the Golgi apparatus." (PMID 40815167, 2025).
metabolic disease (2 papers, 2016 to 2018). A congenital disorder (due to inherited enzyme abnormality) or acquired (due to failure of a metabolically important organ) disorder resulting from an abnormal metabolic process. "Mutations of TMEM165 are linked to a subtype of inborn metabolic diseases affecting the glycosylation pathway, and TMEM165 is a functional homolog of the Golgi-localized ScGdt1." (PMID 29954393, 2018).
skeletal dysplasia (2 papers, 2021 to 2023). Any Mendelian diseases that affects growth and development of the skeleton. "There is a group of CDGs, including ALG12-CDG, ALG3-CDG, ALG9-CDG, ALG6-CDG, PGM3-CDG, CSGALNACT1-CDG, SLC35D1-CDG, and TMEM-165 with well-defined skeletal dysplasia." (PMID 34441372, 2021). "Contrary to PMM2-CDG, all remaining CDG, including ALG12-CDG, ALG3-CDG, ALG9-CDG, ALG6-CDG, PGM3-CDG, CSGALNACT1-CDG, SLC35D1-CDG and TMEM-165, are characterized by well-defined skeletal dysplasia." (PMID 34441372, 2021). "Contrary to PMM2-CDG, skeletal dysplasia was well characterized in other CDGs, including ALG12-CDG, ALG3-CDG, ALG9-CDG, ALG6-CDG, PGM3-CDG, CSGALNACT1-CDG, SLC35D1-CDG and TMEM165-CDG." (PMID 34441372, 2021). "Two of the glycosylation defects, TMEM165-CDG and CSGALNACT1-CDG, are characterized by skeletal dysplasia and abnormal cartilage development." (PMID 34441372, 2021).
TMEM165 also shares sentences with these, for which no sentence is quoted: disorder of glycosylation (2 papers); autistic spectrum disorder (1); bipolar disorder (1); congenital cardiomyopathies (1); COVID-19 (1); cutis laxa (1); depressive disorder (1); Friedreich ataxia (1); genetic disease (1); Macrocephaly (1); microcephaly (1); neurological disorder (1).